TKTL1 (transketolase like 1)
Diseases named in the same sentence as TKTL1 in open-access papers (continued):
Sharing a sentence is not in itself a finding about the gene and the disease.
melanoma (continued). "We found a significant tendency toward co-occurrence of many CTAgs with TKTL1 expression in melanoma tumors." (PMID 26907172, 2016). "In melanoma tumors, we have identified that TKTL1 and CTAgs showed significant correlation in expression." (PMID 26907172, 2016). "Taken together, our data suggests that a subset of melanomas with defective methylation rely on TKTL1-dependent aerobic glycolysis and have enhanced tumorigenesis." (PMID 26907172, 2016). "High magnification image shows that TKTL1 localization is predominantly cytosolic and membrane staining is also seen in some melanoma tumor cells." (PMID 26907172, 2016). "The elevated expression of TKTL1 increases glucose use and lactate production; consequently, melanoma cells with high TKTL1 expression show increased proliferation and metastatic potential, demonstrating a connection between aberrant DNA methylation patterns and altered metabolic pathways." (PMID 40573249, 2025). "In melanoma X-chromosome coded molecules that can be affected include the CTAg and TKTL1." (PMID 26907172, 2016). "Given that TKTL1 is also an X chromosome coded molecule (Xq28) that, like the CTAg, is generally repressed in somatic tissues, we sought to determine if DNA hypomethylation also induced aberrant expression of TKTL1 in melanoma and to assess its role in promoting the Warburg effect in melanoma cells." (PMID 26907172, 2016). "Melanoma samples were further sub-divided into two groups, primary (n = 82) and metastatic (n = 303) in order to examine the role of DNA methylation in regulation of TKTL1 gene expression within primary and metastatic melanoma samples." (PMID 26907172, 2016). "Our data provide evidence for an important role of TKTL1 in aerobic glycolysis and tumor promotion in melanoma that may result from defective promoter methylation." (PMID 26907172, 2016). "This epigenetic change may enable the natural selection of tumor cells with a metabolic phenotype and thereby provide a potential therapeutic target for a subset of melanoma tumors with elevated TKTL1 expression." (PMID 26907172, 2016). "We demonstrated that the TKTL1 promoter could be activated by treatment with 5-aza-2’-deoxycytidine (5aza) thereby inducing TKTL1 expression in melanoma cells." (PMID 26907172, 2016). "Although TKTL1 expression in conjunctival melanoma tumors has been reported, the mechanism by which expression becomes unregulated and the functional consequences of aberrant TKTL1 expression in melanoma remains unclear and these warrant further investigation." (PMID 26907172, 2016). "Additionally, to our knowledge, this is the first study evaluating the effect of TKTL1 expression on metabolic and cellular functions in melanoma." (PMID 26907172, 2016). "Collectively, these results showed that TKTL1 enhanced aerobic glycolysis in melanoma." (PMID 26907172, 2016). "Moreover, we could demonstrate that the TKTL1 promoter is hypomethylated in melanoma cells compared with melanocytes and consequently TKTL1 expression could be induced by incubation of melanoma cells with 5aza." (PMID 26907172, 2016). "However, little is known about the methylation status of TKTL1 in melanoma." (PMID 26907172, 2016). "Although our results suggest that TKTL1 could be a therapeutic target in melanoma, treatment with oxythiamine, a thiamine antagonist, was ineffective even though it was previously shown to decrease proliferation in tumors with high TKTL1 expression." (PMID 26907172, 2016). "Overall, these results indicate that TKTL1 levels may affect melanoma cell proliferation." (PMID 26907172, 2016). "We investigated whether TKTL1 plays a similar role in melanoma." (PMID 26907172, 2016). "Our data suggests that we cannot rule out the possibility that TKT acts in concert with TKTL1 as we observed that TKT is highly expressed in melanoma cell lines and knockdown of TKTL1 impacts TKT expression, if only modestly." (PMID 26907172, 2016).
cervical cancer (7 papers, 2009 to 2025). A primary or metastatic malignant neoplasm involving the cervix. "The Apo10, TKTL1, and APT levels were significantly higher in the cervical cancer group than in the control group (Apo10:139 vs. 132, TKTL1:121 vs. 114, APT: 260 vs. 246)." (PMID 40720083, 2025). "In recent years, a lot of research is focused on TKTL1, and find that TKTL1 is highly expressed in lung cancer, cervical cancer, esophageal squamous cell carcinoma." (PMID 35110545, 2022). "In a word, TKTL1 plays an important role in total transketolase activity and proliferation of tumor cells in uterine cervix cancer." (PMID 19331662, 2009). "In order to explore the effect of TKTL1 on cell proliferation of cervix cancer cell, we transfected the HeLa cells and End1/E6E7 cells with siRNA TKTL1 construct." (PMID 19331662, 2009). "So, we think that strong TKTL1 expression was correlated to fast proliferation of cervix cancer cells." (PMID 19331662, 2009). "The expression of the three putative protein biomarkers we evaluated, i.e., B-MYB, CIP-2A, and TKTL1, was known to increase in histopathology sections of CIN2+ and of cervical carcinoma cones." (PMID 31001477, 2019). "When human cervical cancer HeLa cells were synchronized to G1/S phase by double thymidine, endogenous levels of TKTL1, but not TKT and TKTL2, increased." (PMID 31175280, 2019). "But, the relative contributions of TKTL1 gene to energy metabolism and cell proliferation in uterine cervix cancer have not been investigated." (PMID 19331662, 2009). "After the expression of TKTL1 was silenced, the proliferation of uterine cervix cancer cells was significantly inhibited; there was no significant change in normal cervical epithelial cells." (PMID 19331662, 2009).
gastric cancer (6 papers, 2006 to 2024). A primary or metastatic malignant neoplasm involving the stomach. "Staiger demonstrated that TKTL1 upregulation is a common phenomenon in gastric cancer and cancer of the gastroesophageal junction." (PMID 19331662, 2009). "Two of five gastric carcinomas and two of five lung adenocarcinomas had greater than 10-fold overexpression of TKTL1, whereas TKT expression was unchanged in all tested carcinoma tissues (not shown)." (PMID 16465194, 2006). "Staiger found that the upregulation of TKTL1 is a common phenomenon in gastric cancer and cancer of the gastroesophageal junction leading to an enhanced, oxygen-independent glucose usage which might contribute to a more aggressive tumor growth." (PMID 19331662, 2009). "In addition, the high expression of MET and CLDN9 may potentially predict the prognosis of gastric cancer patients, whereas the role of TKTL1 remains unclear." (PMID 37980488, 2023). "A gastric carcinoma specimen that we found to have 1000-fold overexpression of TKTL1 mRNA when compared to the corresponding normal tissue showed a strong overexpression of the TKTL1 protein on Western blot level as well as a strong TKTL1 immunoreactivity on paraffin sections." (PMID 16465194, 2006). "The expression of the TKTL1 proteinis significantly correlated with increased tumor size, invasion, lymph nodemetastasis, and TNM stage in gastric cancer." (PMID 33503201, 2021). "Immunohistochemical analysis of two gastric carcinoma samples without overexpression of TKTL1 transcript did not reveal TKTL1 protein expression." (PMID 16465194, 2006).
lung cancer (6 papers, 2008 to 2025). A malignant neoplasm involving the lung. "The immunohistochemical stainings displayed elevated expression of TKTL1 in human lung cancer: 40.9% expressed TKTL1 weakly (score 1), 38.6% moderately (score 2), 17.1% strongly (score 3), and 3.4% of the tumors were TKTL1-negative (score 0)." (PMID 18700018, 2008). "These analyses demonstrated that mRNA expression of G6PD, glutaminase (GLS), hydroxy-prostaglandin dehydrogenase 15-(NAD) [HPGD], TKT, TALDO1, ribulose-5-phosphate-3-epimerase (RPE), and transketolase-like-1 (TKTL1) were more abundant in lung cancer patient samples." (PMID 34827081, 2021). "Transketolase-like-protein 1 (TKTL1) protein, a transketolase associated with the condition of aerobic fermentation is overexpressed in lung cancer cells resulting in a higher amount of ribose-5-phosphate (ribose-5-P) than needed for de novo synthesis of purines and pyrimidines." (PMID 31803611, 2019). "Hence we investigated a capacious collective of 88 formalin-fixed non-small cell lung cancer (NSCLC)-tissues (39 adenocarcinomas; 49 squamous cell carcinomas) by immunohistochemistry to describe TKTL1 protein expression in human lung carcinomas." (PMID 18700018, 2008). "Although we describe the expression of TKTL1 in lung cancers, we need to state that up till now there is no scientific indication for any treatment regimens based upon these findings." (PMID 18700018, 2008).
non-small cell lung carcinoma (6 papers, 2006 to 2023). A group of at least three distinct histological types of lung cancer, including non-small cell squamous cell carcinoma, adenocarcinoma, and large cell carcinoma. "In a recent study we were able to demonstrate that overexpression of TKTL1 is associated with a poor outcome in patients with non small cell lung cancer (NSCLC)." (PMID 20385008, 2010). "We investigated TKTL1-expression in 88 human, formalin-fixed non-small cell lung cancer tissues and 24 carcinomas of the breast by immunohistochemical stainings applying a 0 to 3 staining-score system (3 = strongest expression)." (PMID 18700018, 2008). "Non-small-cell lung cancer cells were strongly positive for TKTL1 within the cytoplasm, whereas nuclear staining was absent." (PMID 16465194, 2006).
oral squamous cell carcinoma (6 papers, 2017 to 2025). "Another way of assessing successful surgical resection, relying on the evaluation of postoperative Apo10- and transketolase like 1 (TKTL1)-expressing monocytes, has been tested in oral squamous cell carcinoma (OSCC)." (PMID 33673461, 2021). "The detection of Apo10 and TKTL1 in blood macrophages allowed a sensitive (95.8%) and specific (97.3%) detection of prostate, breast and oral squamous cell carcinomas." (PMID 28425973, 2017).
nasopharyngeal carcinoma (5 papers, 2009 to 2020). A carcinoma arising from the nasopharyngeal epithelium. "Applying siRNA targeting TKTL1 in nasopharyngeal carcinoma cell lines CNE2 and HONE1, Dong and Wang reported a drop in cell viability and in levels of NADPH and ribose 5-phosphate." (PMID 30044385, 2018). "Moreover, knockdown of transketolase-like 1, which functions similarly to transketolase, increases cisplatin cytotoxicity in nasopharyngeal carcinoma cells by reducing ribose 5-phosphate, and therefore PRPP27." (PMID 33199755, 2020). "Evidence implicates that the PPP is controlled by transketolase-like 1 (TKTL1) activity, and the knockdown of TKTL1 leads to a significant decrease of NADPH and ribose-5-phosphate levels in nasopharyngeal carcinoma cells." (PMID 31415630, 2019). "Dong and Wang demonstrated that human nasopharyngeal carcinoma (NPC) cell lines CNE1 and HONE1, present increased levels of transketolase-like protein 1 (TKTL1)." (PMID 32023830, 2020).
glioblastoma (4 papers, 2013 to 2024). The most malignant astrocytic tumor (WHO grade IV). "Among the downregulated genes, ACTC1 is an actin involved in the migration of astrocyte-derived glioblastoma cells, while TKTL1 functions in the generation of neurons." (PMID 38900784, 2024). "Increased levels of TKTL1 mRNA expression and transcription are observed in human glioblastoma tissue and glioma cell lines." (PMID 38786726, 2024). "We therefore examined TKTL1 expression in cultured cells derived from a patient’s primary and recurrent glioblastoma." (PMID 30044385, 2018). "Although the overexpression of TKTL1 takes also place in carcinomas, sarcomas, glioblastomas, lymphomas, and leukemias, the percentage of tumors overexpressing TKTL1 is lower compared to Apo10." (PMID 24304513, 2013). "Our observation that TKTL1 was upregulated in a case of recurrent glioblastoma in comparison to the primary tumor is compatible with a role of TKTL1 in the process of tumor evolution in vivo, with tumor hypoxia, which is known to increase at recurrence, as the primary selective pressure." (PMID 30044385, 2018).
glioma (4 papers, 2015 to 2024). A benign or malignant brain and spinal cord tumor that arises from glial cells (astrocytes, oligodendrocytes, ependymal cells). "Study has shown that TKTL1 is significantly correlated with the expression level of phosphorylated AKT in star glioma tissues." (PMID 34922556, 2021). "Study has shown that TKTL1 was significantly correlated with the expression level of p-AKT in star glioma tissues." (PMID 34922556, 2021). "In the present in vitro study using LNT-229 glioma cells, we analyzed the impact of TKTL1 gene suppression on basic metabolic parameters and on survival following oxygen restriction and ionizing radiation." (PMID 30044385, 2018). "ROS analysis and transient knockdown of TKTL1 in T98G cells confirmed this finding in another glioma cell line." (PMID 30044385, 2018). "In LNT-229 glioma cells used for our experiments, TKTL1 was upregulated under hypoxic conditions." (PMID 30044385, 2018). "Further studies are necessary to examine whether strategies that antagonize TKTL1 function will be able to restore the sensitivity of glioma cells towards irradiation and antiangiogenic therapies in the more complex in vivo environment." (PMID 30044385, 2018). "An overexpression of TKTL1 in glioma, as well as a correlation with tumor grade has been reported." (PMID 30044385, 2018).
leukemia (4 papers, 2013 to 2022). A malignant (clonal) hematologic disorder, involving hematopoietic stem cells and characterized by the presence of primitive or atypical myeloid or lymphoid cells in the bone marrow and the blood. "Furthermore, others demonstrated that siRNA knockdown of TKTL1 in cultured human leukemia cells caused a significant decrease in TKT activity that was measured by glyceraldehyde-3-P production in the two-substrate X5P and ribose-5-P reaction." (PMID 30646877, 2019). "However, to date, there has been little research regarding the importance of TKTL1 for the metabolic response triggered by hypoxia in leukemia and its specific role during metabolic reprogramming of AML cells towards hypoxia remains unknown." (PMID 35408935, 2022). "Increased expression of transketolase (TKT) and its isoform transketolase-like-1 (TKTL1) has been related to the malignant leukemia phenotype through promoting an increase in the non-oxidative branch of the pentose phosphate pathway (PPP)." (PMID 35408935, 2022). "Transduction of human THP-1 leukemia cells with a lentiviral vector expressing a TKTL1-specific shRNA (THP-1KD) specifically downregulated TKTL1 but not TKT (changed by 4.0 ± 1.2%; n = 3; p = NS)." (PMID 27391434, 2016). "However, TKTL1’s role in triggering metabolic reprogramming under hypoxia in leukemia cells has never been characterized." (PMID 35408935, 2022).
ovarian carcinoma (4 papers, 2009 to 2024). A malignant neoplasm originating from the surface ovarian epithelium. "We evaluated the usefulness of YAP, TEAD4, SMAD2, SMAD3, H2A.X, ALD1A1, CD71, TKT and TKTL1 as diagnostic or prognostic markers in patients with ovarian cancer." (PMID 34205023, 2021). "The increased expression of TKTL1 in ovarian cancer tissue compared to those of health was confirmed in ovarian cancer." (PMID 37750325, 2024). "A close correlation of TKTL1 expression with the overall survival (OS) was also demonstrated in all ovarian cancer patients." (PMID 34205023, 2021). "The H2A.X, CD71, SMAD3 and 4, TKT, and TKTL1 proteins require further studies to confirm their suitability for clinical use in ovarian cancer patients." (PMID 34205023, 2021). "We evaluated the differences in the expression of the YAP, TEAD4, SMAD2, SMAD3, H2A.X, ALD1A1, CD71, TKT, and TKTL1 in ovarian cancers and benign cysts." (PMID 34205023, 2021).
head and neck cancer (3 papers, 2015 to 2016). A primary or metastatic malignant neoplasm affecting the head and neck. "Expression of TKTL1 has been reported to be controlled by methylation and demethylation of TKTL1 has been previously reported in lung and head and neck cancers." (PMID 26907172, 2016). "The epigenetic reactivation of TKTL1 occurs simultaneously with DNA hypomethylation of CTAgs in head and neck cancer." (PMID 26907172, 2016). "Simultaneous reactivation of TKTL1 with CTAg such as the melanoma antigen family (MAGE-A) has been reported in lung and head and neck cancers." (PMID 26907172, 2016).
hepatocellular carcinoma (3 papers, 2009 to 2022). A malignant tumor that arises from hepatocytes. "TKTL1 plays an important role in tumor proliferation in gastric, colon and hepatocellular carcinomas." (PMID 26907172, 2016). "We obtained a prognostic signature including eight hypoxia genes (ENO2, KDELR3, PFKP, SLC2A1, PGF, PPFIA4, SAP30, and TKTL1) and further established a hypoxia-related prognostic ceRNA network including 17 lncRNAs, six miRNAs, and seven mRNAs for hepatocellular carcinoma." (PMID 36362375, 2022). "Among the eight mRNAs in the model, the up-expressions of TKTL1, KDELR3, PFKP, SLC2A1, and PGF in hepatocellular carcinoma were confirmed in previous experimental studies, while the over-expression of SAP30 in HCC was reported in an earlier computational study." (PMID 36362375, 2022).
laryngeal carcinoma (3 papers, 2009 to 2022). Carcinoma that arises from the laryngeal epithelium. "It has also been reported that upregulation of TKTL1 is associated with poor prognosis in patients with certain type of malignancies, such as colon, urothelial, rectum, and laryngeal cancers." (PMID 36009359, 2022).
papillary thyroid carcinoma (3 papers, 2006 to 2017). "Antibody reactivity against TKTL1 was assessed as above, on the same 3 normal mammary glands and 3 simple tubulo-papillary carcinomas (1 well-differentiated and 2 moderately differentiated) by Western immunoblotting." (PMID 28143530, 2017).
renal carcinoma (3 papers, 2006 to 2024). A carcinoma arising from the epithelium of the renal parenchyma or the renal pelvis. "Despite this knowledge, the precise relationship between TKTL1 and renal cancer, as well as the underlying mechanisms involved, remain inadequately understood." (PMID 38675412, 2024). "We also studied the relationship between TKTL1 expression and response to PD-1 blocker immunotherapy in renal cancer." (PMID 38675412, 2024). "We discovered that the manifestation of TKTL1 varied across various types of cancers and exhibited diverse patterns in terms of prognosis, particularly in cases of renal carcinoma." (PMID 38675412, 2024). "Further, with renal cancer another carcinoma displayed intensively elevated transketolase activity due to TKTL1-upregulation." (PMID 18700018, 2008). "This may be the underlying reason why TKTL1 recruits T cells in KIRC and has different prognostic relevance in the three types of renal cancer." (PMID 38675412, 2024).
colitis (2 papers, 2021 to 2024). Inflammation of the colon. "In IECs, TKTL1 expression has also been demonstrated to help maintain epithelial barrier function and inhibit apoptosis-induced colitis." (PMID 39199837, 2024). "Furthermore, lack of transketolase-like 1 (TKTL1), which belongs to the TKT gene family, aggravates murine experimental colitis." (PMID 34535624, 2021).